DSG2 (desmoglein 2)
Description:
A component of desmosome cell-cell junctions which are required for positive regulation of cellular adhesion. Involved in the interaction of plaque proteins and intermediate filaments mediating cell-cell adhesion. Required for proliferation and viability of embryonic stem cells in the blastocyst, thereby crucial for progression of post-implantation embryonic development (By similarity). Maintains pluripotency by regulating epithelial to mesenchymal transition/mesenchymal to epithelial transition (EMT/MET) via interacting with and sequestering CTNNB1 to sites of cell-cell contact, thereby reducing translocation of CTNNB1 to the nucleus and subsequent transcription of CTNNB1/TCF-target genes. Promotes pluripotency and the multi-lineage differentiation potential of hematopoietic stem cells. Plays a role in endothelial cell sprouting and elongation via mediating the junctional-association of cortical actin fibers and CDH5. Promotes cardiomyocyte cell homeostasis and desmosome junction formation at intercalated disks, as a result plays a role in the maintenance of cardiac conduction and heart chamber integrity (By similarity). Positively regulates pancreatic islet development and maintenance of endothelial cell barrier integrity in the pancreas, therefore involved in the controlled release of insulin from islet cells into the circulation in response to glucose (By similarity). Plays a role in limiting inflammatory infiltration and the apoptotic response to injury in kidney tubular epithelial cells, potentially via its role in maintaining cell-cell adhesion and the epithelial barrier. Acts as a positive modulator of CSK and EGFR activation via sequestering them away from lipid rafts, this is independent of its role in desmosome cell junctions. Also disrupts the localization of CAV1 to lipid rafts resulting in its distribution throughout the cytoplasm. (Microbial infection) Required for fiber protein-mediated Human Adenovirus 55 and 14a infection; via its interaction with fiber protein.
Synonyms: CDHF5; HDGC
Tractability: Small molecule: it has a high-quality binding pocket. Antibody: UniProt places it where antibodies can reach, with high confidence; its Gene Ontology location is reachable by antibodies, with high confidence; UniProt predicts a signal peptide or a membrane-spanning region. PROTAC: ubiquitination databases record sites on it; its protein half-life has been measured.
Gene: Protein-coding gene on chromosome 18 (31,497,624 to 31,551,351, forward strand). Ensembl gene ENSG00000046604.
Subcellular location: Cell membrane; Cell junction, desmosome; Cytoplasm; Secreted
Subcellular location (Human Protein Atlas): Cell Junctions; Plasma membrane; Vesicles
Pathways (Reactome):
Signal Transduction: RAC2 GTPase cycle; RAC3 GTPase cycle; RHOG GTPase cycle
Developmental Biology: Formation of the cornified envelope; Keratinization
Programmed Cell Death: Apoptotic cleavage of cell adhesion proteins
Gene Ontology:
Molecular function: cell adhesion molecule binding; protein binding; protein dimerization activity; calcium ion binding; cell adhesive protein binding involved in bundle of His cell-Purkinje myocyte communication; protein homodimerization activity
Biological process: bundle of His cell-Purkinje myocyte adhesion involved in cell communication; cell adhesion; desmosome organization; homophilic cell-cell adhesion; mesenchymal to epithelial transition; negative regulation of apoptotic process; negative regulation of endothelial cell differentiation; negative regulation of epithelial to mesenchymal transition; positive regulation of cell adhesion; positive regulation of protein localization to cell-cell junction; positive regulation of sprouting angiogenesis; Purkinje myocyte development; regulation of heart rate by cardiac conduction; regulation of protein localization; regulation of ventricular cardiac muscle cell action potential; cell-cell adhesion; desmosome assembly; endocrine pancreas development; positive regulation of stem cell population maintenance; regulation of cardiac conduction; stem cell proliferation; negative regulation of inflammatory response to wounding
Cellular component: cell junction; cell surface; cytoplasm; desmosome; extracellular exosome; extracellular region; intercalated disc; plasma membrane; cell-cell junction; cornified envelope; membrane
Genetic constraint (gnomAD): Loss-of-function variants: 40 observed, 68.19 expected, observed/expected ratio (o/e) 0.59, 90% interval 0.46 to 0.76. The upper end of that interval is the gene's LOEUF score, 0.76, which puts it in group 3 of 6, group 1 being the genes least tolerant of losing a copy. Missense variants: 1,206 observed, 1,344.1 expected, observed/expected ratio (o/e) 0.9, 90% interval 0.86 to 0.94. Synonymous variants: 406 observed, 480.6 expected, observed/expected ratio (o/e) 0.84, 90% interval 0.78 to 0.92.
Gene-disease validity (ClinGen):
ClinGen rates the evidence that DSG2 causes each of these diseases.
arrhythmogenic right ventricular cardiomyopathy (autosomal dominant): Definitive.
dilated cardiomyopathy 1BB (autosomal dominant): Limited.
Homologues: Orthologues: chimpanzee DSG2 (99% identical), macaque DSG2 (96% identical), rabbit DSG2 (79% identical), dog DSG2 (78% identical), pig DSG2 (77% identical), mouse Dsg2 (77% identical), rat Dsg2 (74% identical), guinea pig DSG2 (67% identical), tropical clawed frog dsg2 (41% identical), zebrafish si:ch73-74h11.1 (27% identical). Paralogues in human: DSG4 (35% identical), DSG3 (34% identical), DSG1 (32% identical), DSC1 (21% identical), DSC2 (21% identical), DSC3 (21% identical).
Diseases named in the same sentence as DSG2 in open-access papers:
DSG2 is named in the same sentence as 182 diseases in open-access papers, as found by Europe PMC text mining. Sharing a sentence is not in itself a finding about the gene and the disease. The quoted sentences say what the papers report.
arrhythmogenic right ventricular cardiomyopathy (34 papers, 2012 to 2026). "It has been proven that mutations in the glycosylation sites of DSG2 have been associated with weakened myocardial desmosomes in arrhythmogenic right ventricular dysplasia/cardiomyopathy (ARVD/C)." (PMID 40072053, 2025). "Mapping of disease-associated proteins interestingly showed desmoglein-2, for which defects in this protein are known to cause Arrhythmogenic Right Ventricular Dysplasia/Cardiomyopathy, which was present predominantly in the outer wall of the left ventricle." (PMID 39202712, 2024). "Loss of DSG2 function in humans is directly linked to arrhythmogenic right ventricular cardiomyopathy (ARVC), an autosomal recessive disease underpinned by myocyte apoptosis and fibrous degeneration of the myocardium." (PMID 32095325, 2020). "Patients with heterozygous mutations in JUP have been diagnosed with HCM, and reduced cardiac DSG2 levels appear to be specifically associated with arrhythmogenic right ventricular cardiomyopathy (ARVC)." (PMID 32344918, 2020). "Both MTHFR-associated thrombophilia and DSG2-associated arrhythmogenic right ventricular dysplasia or cardiomyopathy were autosomal dominant inherited disorders." (PMID 31948402, 2020). "A targeted genetic testing for idiopathic ventricular fibrillation revealed a mutation in the desmoglein-2 (DSG2) gene involved in arrhythmogenic right ventricular cardiomyopathy (ARVC)." (PMID 30524916, 2018). "Mutations in the DSG2-gene are regarded to cause arrhythmogenic (right ventricular) cardiomyopathy (ARVC) which is a rare but severe heart muscle disease." (PMID 29062102, 2017). "A final thorough analysis of all predicted deleterious variants in the exome sequencing of patient II.6 showed a novel nonsense mutation in desmoglein (DSG2), a gene implicated in arrhythmogenic right ventricular dysplasia." (PMID 28979898, 2017). "Desmoglein-2 mutations are detected in 5–10% of patients with arrhythmogenic right ventricular cardiomyopathy (ARVC)." (PMID 38790949, 2024). "Autoantibodies to desmoglein-2 have been associated with arrhythmogenic right ventricular cardiomyopathy (ARVC) in people." (PMID 36977772, 2023). "Of note, a large number of studies have shown an association of mutations in DSG2 and arrhythmogenic right ventricular cardiomyopathy (ARVC)." (PMID 34202524, 2021). "Loss of Dsg2 is embryonically lethal while mutations in Dsg2 and Dsc2 cause arrhythmogenic right ventricular cardiomyopathy (ARVC), a hereditary heart disease." (PMID 29999492, 2018). "Although numerous sequence variants in desmoglein-2 (DSG2) have been associated with arrhythmogenic right ventricular cardiomyopathy (ARVC), the functional impact of new sequence variations is difficult to estimate." (PMID 23071725, 2012). "The presence of multiple pathogenic variants in desmosomal genes (DSC2, DSG2, DSP, JUP, and PKP2) in patients with arrhythmogenic right ventricular cardiomyopathy (ARVC) has been linked to a severe phenotype." (PMID 37418234, 2023). "In keeping with its role in tissue integrity, loss of DSG2 function in humans is directly linked to arrhythmogenic right ventricular cardiomyopathy (ARVC), an autosomal recessive disease underpinned by myocyte apoptosis and fibrous degeneration of the myocardium." (PMID 27338829, 2016). "Genetic variants in desmosomal proteins (e.g., PKP2, DSP, DSG2, DSC2) are strongly associated with arrhythmogenic right ventricular cardiomyopathy (ARVC), while mutations in sarcomeric and cytoskeletal genes (e.g., MYH7, LMNA, DES) are linked to hypertrophic and dilated cardiomyopathies." (PMID 41596321, 2026). "Arrhythmogenic right ventricular cardiomyopathy (ARVC) is a rare but severe cardiac condition frequently associated with mutations of proteins involved in desmosomes (Plakophilin-2, Desmoplakin, Desmoglein-2, and Desmocollin-2), structures involved in the cell–cell interactions." (PMID 33329039, 2020).
arrhythmogenic right ventricular cardiomyopathy (continued). "Mutations of Dsg2 are detected in patients with arrhythmogenic right ventricular cardiomyopathy (ARVC), and expression of Dsg2 is increased in several epithelial-derived malignancies including basal-cell carcinomas, squamous cell carcinomas, and metastatic prostate cancer." (PMID 30790141, 2019). "Variants in the DSG2 gene are mainly associated with arrhythmogenic right ventricular cardiomyopathy (ARVC) and not with HCM." (PMID 30847665, 2019). "Various genes coding cytoskeleton proteins such as DSC2 (desmocollin-2) and DSG2 (desmoglein 2) have also been associated with DCM and arrhythmogenic right ventricular cardiomyopathy (ARVC)." (PMID 32005173, 2020). "Another cohort study identified anti-desmoglein-2 (Anti-DSG2) antibodies as a sensitive and specific biomarker for arrhythmogenic right ventricular cardiomyopathy (ARVC)." (PMID 35350762, 2022). "This DSG2 mutation was not seen among 7855 cardiomyopathy patients with DCM or arrhythmogenic right ventricular cardiomyopathy (ARVC)." (PMID 33949662, 2021).
cardiomyopathy (34 papers, 2013 to 2025). A disease of the heart muscle or myocardium proper. "The global DSG2 deletion is embryonically lethal in mice, while the deletion of a fragment within the first and second extracellular domains of murine DSG2 causes a similar cardiomyopathy phenotype." (PMID 40072053, 2025). "Here, we identified four unrelated cardiomyopathy patients carrying heterozygous DSG2 p.Arg119Ter variants who exhibited various clinical courses." (PMID 39706847, 2024). "In humans, heterozygous PKP2 and DSG2 mutations lead to ARVC, but in mice, homozygous deletion of Dsg2 and Pkp2 in the mouse heart is required to elicit cardiomyopathy and to define NF-κB activation, since heterozygous deletion has little phenotype in mice." (PMID 38768074, 2024). "DSG2-p.S363X is a null variant, and previously, it has been shown that DSG2 deficiency causes cardiomyopathy in mice and humans (very strong criterion, PVS1, ACMG guidelines)." (PMID 34202524, 2021). "In this report, we identified a case of desmoglein-2-deficient cardiomyopathy caused by a homozygous stop-gain mutation, which was initially diagnosed as idiopathic DCM." (PMID 33949662, 2021). "Here, we identify a case of desmoglein-2-deficient cardiomyopathy caused by a rare homozygous stop-gain mutation." (PMID 33949662, 2021). "Our findings confirm the presence of a desmoglein-2-deficient cardiomyopathy among clinically diagnosed dilated cardiomyopathies." (PMID 33949662, 2021). "The global knock-out of Dsg2 is embryonically lethal whereas the cardiac specific knock-out of Dsg2 causes severe cardiomyopathy." (PMID 28339476, 2017). "Upregulated genes linked to cardiomyopathy included Pkp2, Dst, Dsg2 and Jup; downregulated genes included Pkp1, Dsg1a, Pkp4, Vcl, Gja1 and Ctnna1." (PMID 26935106, 2016). "In addition to LMNA, mutations to CAV3, ACTA1, ACTC1, DYSF, and DSG2 are linked to cardiomyopathies and encode proteins that are long-lived in the heart." (PMID 37162946, 2023). "This indicates that especially the protein integration and degradation of the desmosomal cadherins in the desmosome might be affected in cardiomyopathy related DSG2 mutations." (PMID 29062102, 2017). "In addition to the well-recognised link between DSG2 mutation and cardiomyopathy in humans, a second clinical manifestation linked to DSG2 loss-of-function has been identified in patients with systemic sclerosis (SSc, scleroderma)." (PMID 27338829, 2016). "Since DSG2 is responsible for the formation and maintenance of the cell structures, there are two strategies targeting DSG2 for the treatment of cardiomyopathies." (PMID 40072053, 2025). "Altogether, we conclude that ER/SR stress and autophagy are pathological traits in Dsg2-related cardiomyopathy." (PMID 35011658, 2021). "Others are associated with cardiomyopathy, such as that observed in DMD and GRMD (desmocollin 2 – DSC2; desmoglein 2 – DSG2)." (PMID 27549615, 2016). "No cardiomyopathy-related pathological variants other than DSG2 p.Arg119Ter were identified in Pt-2." (PMID 39706847, 2024). "No cardiomyopathy-related pathological variants other than the DSG2 p.Arg119Ter variant were identified in Pt-4, although Pt-4 was diagnosed with HCM." (PMID 39706847, 2024). "In this study, we identified four unrelated cardiomyopathy patients with heterozygous DSG2 p.Arg119Ter variants among 808 patients with nonischemic cardiomyopathy." (PMID 39706847, 2024). "We recently reported a case of desmoglein-2-deficient cardiomyopathy caused by a rare homozygous stop-gain mutation and established isogenic iPSC-CMs from the patient lacking desmoglein-2." (PMID 35063130, 2022). "Therefore, different conditional knock-out, knock-in, and transgenic mouse models for Dsg2 leading to murine arrhythmogenic cardiomyopathies have been developed." (PMID 33917638, 2021).
cardiomyopathy (continued). "Besides the hub genes of MYBPC3, MYH7, and DSP, these subnetworks also include several genes that have been implicated in cardiomyopathy, such as TPM1, ACTC1, DES, TCAP, JUP, and DSG2." (PMID 32344918, 2020). "Here, we identified four unrelated patients with cardiomyopathy with heterozygous DSG2 p.Arg119Ter variants among 808 patients with nonischemic cardiomyopathy; the allele frequency was 0.0037, which is more than 50-fold greater than that reported in the general Japanese population." (PMID 39706847, 2024). "The majority of the VUS has been identified in genes previously having been reported to be associated with cardiac channelopathies (SCN5A, AKAP9, RYR2) and cardiomyopathies (RBM20, RAF1, DSG2)." (PMID 33789662, 2021). "Cardiac specific lack of desmoglein-2 leads to severe cardiomyopathy, whereas overexpression does not." (PMID 28339476, 2017). "Cardiomyopathy can also occur with or without left ventricular dysfunction, as in left ventricular non-compaction cardiomyopathy (LVNC), which is a rare heart disease occurring due to two (likely) pathogenic nonsense mutations: DSG2-p.S363X and TBX20-p.D278X." (PMID 36475220, 2022).
colon carcinoma (21 papers, 2013 to 2024). "Briefly, studies related to SCC, BCC, breast cancer, cervical cancer, colon cancer, lung cancer, multiple myeloma, and ovarian cancer are predominantly associated with a pro-tumorigenic function for DSG2." (PMID 38188287, 2023). "In colon cancer, loss of Dsg2 leads to a compensatory increase in Dsc2 expression and the increased Dsc2 suppresses cell proliferation by inhibition of EGFR downstream signaling such as Src." (PMID 32989241, 2021). "However, shDsg2 or shDsc2 MCF-7 cells exhibited enhanced malignancy in our study while Dsg2-deficient cervical cancer and colon cancer cells showed inhibited progression." (PMID 38671389, 2024). "However, DSG2 expression in colon cancer (CC) and its association with CC patients’ overall survival (OS) are still unclear." (PMID 33407183, 2021). "A similar effect of DSC2 and DSG2 mediated cell adhesion on cell aggregation was detected in colon cancer spheroids." (PMID 36927383, 2023). "Downmodulation of DSG2 significantly inhibited the proliferation of colon cancer cells and the progression of non-small cell lung cancer." (PMID 37391503, 2023). "Studies were performed with T84 cells, a human colon cancer cell line that expresses high levels of DSG2 and forms epithelial junctions when cultured in transwells." (PMID 36360292, 2022). "In the context of cancer, DSG2 has been shown to promote the proliferation of colon cancer and non‐small cell lung cancer cells, to support vasculogenic mimicry by melanoma cells and protect epithelial cells from apoptosis." (PMID 34245117, 2022). "Analysis of human colon cancer shows that DSG2 protein expression is increased and mediates the proliferation of colon cancer cells through the EGFR signaling pathway." (PMID 32997416, 2020). "Altered Dsg2 expression also occurs in prostate and colon cancers, suggesting a role for Dsg2 in oncogenesis in a variety of epithelial tissues." (PMID 26918609, 2016). "We, and others have shown that while Dsg2 expression in the interfollicular epidermis is demonstrably low, it is markedly increased in skin, prostate, and colon cancers." (PMID 25785582, 2015). "To further substantiate the functionality of the Dsg2 mAb, we performed dispase-based dissociation assays in a colon carcinoma cell line (Caco-2), in which Dsg2 is the only desmosomal cadherin expressed beside Dsc2." (PMID 23326495, 2013). "Double down-regulation of DSC2 and DSG2 saved the down-regulation of DSG2 alone on the growth inhibition of colon cancer cell lines, suggesting that down-regulation of DSC2 could promote the proliferation of colon cancer cells." (PMID 36367775, 2022). "Dsg2 depletion in SK-CO15 colon cancer cells also disrupts EGFR signaling." (PMID 26918609, 2016). "However unlike HaCaT keratinocytes, loss of Dsg2 does not alter the total level of EGFR in SK-CO15 colon cancer cells." (PMID 26918609, 2016). "DSG2 has been previously reported to facilitate EGFR activity; DSG2/EGFR interaction has demonstrated importance in the development of SCC, colon cancer, and lung adenocarcinoma." (PMID 38188287, 2023). "A study on colon cancer also showed that phosphorylation of the EGFR and downstream signal activation is enhanced by DSG2, where downregulation of DSG2 decreases EGF-induced cell proliferation and suppresses in vivo xenograft tumor growth." (PMID 38188287, 2023). "The effects of Dsg2 antibody and KC21 on ECFC angiogenesis inhibition are comparable to the application of Dsg2 antibody and EC2 domain peptides on disturbing intercellular barriers in human colon carcinoma (Caco) enterocytes." (PMID 30790141, 2019). "Desmoglein-2 (DSG2) and Desmocollin-2 (DSC2) are transmembrane proteins that regulate intercellular connections, contributing to desmosome assembly and playing an important role in colon cancer progression." (PMID 38069408, 2023). "However, in colon cancers and NSCLC, knockdown DSG2 suppressed cell proliferation both in vitro and in vivo." (PMID 32095325, 2020).